ENSG00000288645 (novel protein)
Synonyms: LOC128092252
Gene: Protein-coding gene on chromosome 15 (50,648,802 to 50,686,717, reverse strand). Ensembl gene ENSG00000288645.
Genetic constraint (gnomAD): Loss-of-function variants: 6 observed, 10.8 expected, observed/expected ratio (o/e) 0.56, 90% interval 0.3 to 1.1. Missense variants: 109 observed, 104.16 expected, observed/expected ratio (o/e) 1.05, 90% interval 0.89 to 1.23. Synonymous variants: 45 observed, 38.13 expected, observed/expected ratio (o/e) 1.18, 90% interval 0.93 to 1.51.